BAX (BCL2 associated X, apoptosis regulator)
Diseases named in the same sentence as BAX in open-access papers (continued):
Sharing a sentence is not in itself a finding about the gene and the disease.
cancer (continued). "As many traditional anti-cancer drugs act on the BCL-2/BAX pathway, any disruption of this target may increase resistance to chemotherapy and radiotherapy by elevating the threshold needed for cell death." (PMID 36291779, 2022). "This induction affects the ratio of BCL-2 to BAX, which may result in an alteration of apoptotic impulses and cancer cells’ resistance to therapeutic drugs." (PMID 35328794, 2022). "Among 6 up-regulated cancer driver genes, 4 genes encode proteins known to function as negative regulators of cell proliferation (CDKN2A); inducers of apoptosis (BAX); tumor suppressor (RPL22); inhibitors of transactivation of insulin promoter by recruiting a repressor complex (SPOP)." (PMID 36879662, 2022). "Together, these results support the notion that these tBID mutations found in cancer patients do not affect its ability to activate BAX and BAK, but to induce MOMP in their absence." (PMID 34931711, 2022). "Following the same mental construction, the rarity of complete loss of BAX and BAK from cancer cells may be explained." (PMID 34725331, 2021). "Genetic alterations in the BAX gene may play important role in cancer initiation and progression as it contains series of target genes involving various tumor suppressor genes and oncogenes." (PMID 33708254, 2021). "The effects of flavonoids in pro-apoptotic proteins were not only detected in cancer cell cultures but also in athymic nude mice models, where 23 days of treatment with 0.2–0.4 mg/kg of Genistein was able to significantly increase the levels of BAX and BAK." (PMID 33918290, 2021). "The unusual regulation of BAX localization remains a major question to understand how the apoptotic process is induced (or not) following an apoptotic stimulus such as the one triggered by cancer therapies." (PMID 33920941, 2021). "The association of BAX -248 G>A and BCL2 -938 C>A with different cancers created conflicts." (PMID 33906310, 2021). "Direct activators of BAK may best recruit additional pore-forming BAK and BAX molecules to induce robust apoptosis in cancer cells." (PMID 32327636, 2020). "Therefore, the expression levels of apoptosis-associated proteins (Bcl-xL and BAX) and HIF-1 as markers of cancer cell aggressiveness were assessed." (PMID 32824972, 2020). "Furthermore, C-1305 treatment resulted in increased expression of mitochondrial apoptosis markers Bcl-2-associated X apoptosis regulator (BAX) and Bcl-2-associated agonist of cell death (BAD) in cancer cells, when compared to controls and 16HBE14o- cells." (PMID 32252403, 2020). "Many anti-cancer drugs induce apoptosis through the BAK/BAX-dependent apoptosis pathway, however, whether this pyroptosis was dependent on BAK/BAX is not clear." (PMID 32332857, 2020). "In addition to eliciting BAX/BAK-dependent apoptosis, Obatoclax is able to provoke cell death in BAX/BAK-deficient cancer cells." (PMID 32150830, 2020). "Moreover, BAX can also promote the release of CytC from the mitochondria into the cytoplasm to activate multiple caspases, thus inducing cancer cell apoptosis." (PMID 32973533, 2020). "In addition, we observed an increase in the ratio of Bcl-2/BAX which are important regulators of cell survival and play an important role in development of cancer." (PMID 33251127, 2020).
cancer (continued). "Therefore, it was tempted to clarify the downstream effects of BAX and BAK deficiency in the development of cancer drug resistance." (PMID 31551763, 2019). "Cancer cells evade apoptotic mechanisms through different mechanisms: the most frequent mechanism is represented by overexpression of anti-apoptotic BCL-2 proteins and loss of BAX or BAK; inhibition of caspase function." (PMID 30813354, 2019). "Most scholars have shown that BAX polymorphism is not related to cancer susceptibility, and a small amount of BAX gene polymorphism is associated with cancer susceptibility." (PMID 30024563, 2018). "The BAX gene is a central pro-apoptotic gene that cancause cell death and limit cancer progression." (PMID 29633596, 2018). "PEITC (at 5–10 μM) induces apoptosis in several cell lines by a cancer cell-specific generation of ROS that is related to mitochondrial deregulation and modulation of proteins like Bcl2, BID, BIM, and BAX, causing the release of cytochrome c into cytosol leading to apoptosis." (PMID 29618945, 2018). "In addition, its upregulation also suppresses the apoptosis of the cancer cells by decreasing B‐cell lymphoma 2 (BCL2) and increasing BCL2‐associated X protein (BAX), and baculoviral IAP repeat containing 5 (BIRC5) transcription." (PMID 29473345, 2018). "This hypothesis is supported by published data that TIMP1 is involved in inhibiting apoptosis by suppressing BAX in cancer cells, bone marrow stromal cell line, and mesangial cells." (PMID 29742163, 2018). "However, BAX expression successively decreases as a cancer progresses and is the lowest in patients with distant metastasis." (PMID 28035578, 2017). "BCL-2/BAX ratio also serves as a predictor of drug efficacy and cancer invasiveness." (PMID 28235409, 2017). "Therefore, the authors suggested that decreased UVRAG activity directly influences BAX-induced apoptosis in cancer cells." (PMID 28035578, 2017). "Some scorpion venoms target caspases, mitochondria, Bcl-2, and BAX and may thereby contribute to cancer treatment." (PMID 30873475, 2017). "Small BAX agonists can induce conformational variations by blocking phosphorylation sites to facilitate BAX insertion into mitochondrial membranes and form BAX oligomers, which finally leads to the release of cytochrome c and apoptosis in several types of cancers." (PMID 28556798, 2017). "Western blot analysis revealed up-regulation of pro-apoptotic protein BAX, along with the down-regulation of anti-apoptotic proteins (BCL-XL, Survivin), migration associated proteins (p-FAK, MMP-3) and cancer stem cell (CSC) markers (CD44, Oct-4), which was probably mediated by AKT/c-Jun pathway." (PMID 28036386, 2016). "Similarly, approaches using hypoxia-responsive promoters combined with the cytotoxic protein BAX after viral delivery or hypoxia-dependent E1A expression for hypoxia-targeted virus replication are promising candidates for cancer therapy." (PMID 27458162, 2016). "The transamidation activity of TGM2 has been implicated in apoptosis by interacting with BAX or cross-linking CASP3/Caspase 3 and RB1/pRB to inhibit apoptosis in various cancer cell lines." (PMID 26956429, 2016).
cancer (continued). "Mitochondrial cholesterol loading in cancer cells may account for the recognized mitochondrial dysfunction and resistance to BAX-mediated cell death induced by chemotherapeutic agents that target mitochondria to elicit MOMP." (PMID 27455839, 2016). "Interestingly, the IC50 value of the BAX-Pmut cancer cell lines harboring protein pocket mutations on vinorelbine was significantly lower than that of BAX-WT cancer cell lines (P = 0.02, Wilcoxon test)." (PMID 25360158, 2014). "These properties of BAX protein make it a sound candidate for cancer therapy." (PMID 24073264, 2013). "14-3-3 proteins are dysregulated in cancers and can act as either tumor suppressors (14-3-3σ) or oncogenes (14-3-3β, ζ, γ, or θ) by binding and sequestering phosphorylated pro-apoptotic proteins such as BAX, BAD, ASK1, Foxo1 or Foxo3a." (PMID 23236401, 2012). "Furthermore, our results indicate that LY294002 causes inhibition of tumor growth and increase in lumen formation in C4-HI cancer cells through an intrinsic BAX/mitochondrial/activated caspase-9 apoptotic mechanism." (PMID 20520761, 2010). "This may be related to the proapoptotic effect of BAX on cancer cells." (PMID 41614769, 2025). "Therefore, we took advantage of BAX-deficient LoVo cells to test the hypothesis that an unprimed, incompetent state of TIS cancer cells may inform pan-refractoriness to BH3 senolytics." (PMID 40055336, 2025). "Importantly, by studying the EMT markers and classic proliferation markers, we figured out that BAX may participate in proliferation and metastasis of many cancers, especially in LGG and KIRC." (PMID 39074253, 2024). "Likewise, many cancers exhibit upregulated protein–protein interactions (PPIs) of the anti-apoptotic proteins driven by genomic and epigenomic alterations to suppress the activity of BAX/BAK, thus averting apoptosis initiation." (PMID 39025942, 2024). "In addition, as the BAX serine 184 regulatory site is responsible for subcellular localization and insertion into mitochondrial membranes, the agonists targeting BAX have been developed for cancer treatment." (PMID 38763973, 2024). "We comprehensively investigated cancer-associated somatic mutations affecting the transmembrane domain of BCL2 proteins and elucidated their effect on membrane insertion, hetero-interactions with the pro-apoptotic protein BAX, and modulation of cell death in cancer cells." (PMID 38670940, 2024). "Another study on the same cancer cells explained that ORI‐N more significantly retarded tumor proliferation by causing G2/M‐phase cell cycle arrest and induced apoptosis through BCL‐2/BAX pathway in a concentration‐dependent way, when compared with ORI solution." (PMID 38726411, 2024). "Thus, in this study we have evaluated the relationship between BAX gene and protein expression, survival prognosis, clinical relevance, genetic alteration, Immune infiltration, methylation level and gene enrichment analysis across 33 TCGA cancer types." (PMID 39074253, 2024). "As a result, there is substantial interest in small molecules that can directly activate BAK or BAX, as these molecules could potentially induce cancer cell apoptosis directly or sensitize cancer cells to other anti-cancer treatments if suitably targeted to neoplastic cells." (PMID 37393297, 2023).
cancer (continued). "Because cancer cell lines have different mutational landscape and expression levels of the BCL-2 family proteins, to evaluate the contribution of BAX dimer and monomer more precisely to apoptosis, we generated cells expressing cytosolic BAX dimer or monomer in the same cellular background." (PMID 38104127, 2023). "Although BAX rs4645878 does not appear to play a role in carcinogenesis, it has been suggested that it may be associated with poor prognosis in some cancers." (PMID 38003498, 2023). "Furthermore, a recent study has demonstrated that increased miR-34c-5p expression in NPC cancer cells is associated with reduced cancer cell proliferation, metastasis, and epithelial-mesenchymal transition (EMT) and decreased BCl2/BAX ratio and β-CATENIN gene expression." (PMID 38116556, 2023). "From these three groups, the BAX (pro-apoptotic) and Bcl-2, Bcl-xL or Mcl1 (anti-apoptotic) proteins have gained the most attention over the recent decades, based on their deregulated expression, significance in the development of a number of cancers and their responsiveness to therapeutics." (PMID 34753495, 2021). "D2O-induction of apoptosis has been documented before in a variety of cultured cancer cell lines, involving modulation of apoptotic executioners (such as BAX and BCL2) and markers (including PARP-1 cleavage) through unknown upstream mechanisms responsive to D2O exposure." (PMID 33546433, 2021). "However, BAX deficiency alone does not result in an increased risk to spontaneous cancer formation in mice." (PMID 33162554, 2021). "However, loss of the representative pro‐apoptosis members BAX, BIM and BBC3 is also a common trend in oncogenesis, facilitating tumour formation and progression through genomic deletion, silencing and mutation in several cancers." (PMID 32419250, 2020). "Therefore, we transfected IRX1 in cancer cells and analyzed the mRNA levels of BAX." (PMID 33256112, 2020). "However, we found that PRKN and BAX protein were only slightly upregulated in cancer tissues." (PMID 32649310, 2020). "In addition, BAX expression is very often downregulated in many types of cancer." (PMID 31159324, 2019). "To characterize whether cells that survived 5-FU exposure were related to the cancer stem phenotype, we compared gene expression of genes involved in cell survival (BAX and BCLL2) and drug resistance (ABCG2) among cells surviving 5-FU exposure and control cells." (PMID 28611669, 2017). "Previous studies showed that MALAT-1 promotes cancer progression, mainly through the regulation of gene expression, for example, the epithelial mesenchymal transition associated genes, ZEB1, ZEB2, and Slug and the apoptosis related genes, CASP3, CASP8, BAX, BCL2, and BCL2L1." (PMID 26989678, 2016). "Thus, aberrant expression of Bcl-2 and/or BAX is thought to play a role in cancer development." (PMID 26656462, 2015). "Similar patterns of coding microsatellite instability in MMR-DCF and MMR-deficient cancers suggest that certain combinations of coding microsatellite mutations, including mutations of the HT001, AIM2 and BAX gene, may contribute to the progression of MMR-deficient lesions into MMR-deficient cancers." (PMID 25816162, 2015).
cancer (continued). "This study overcomes these limitations by establishing a sensitized 3D spheroid cancer cell model that employs the adenovirus-mediated gene expressions of tumor-suppressor and pro-apoptotic genes consisting of MOAP-1, BAX, and RASSF1A." (PMID 41874166, 2026). "This potential is evidenced by its ability to modulate the expression of the pro-apoptotic gene BAX and the anti-apoptotic gene BCL-2, thereby inducing apoptosis in cancer cells." (PMID 39918669, 2025). "Even in a BAX/BAK-competent scenario, cancer cells and senescent melanocytes that upregulate the expression of anti-apoptotic BCL-2 family members can also remain completely resistant to the senolytic effects of ABT-263/navitoclax and ABT-737/venetoclax." (PMID 40055336, 2025). "The PI3K/AKT signaling pathway contributes to chemoresistance in cancer by promoting antiapoptopic proteins such as BCL-XL and BCL-2, while inhibiting proapoptotic such as BAX." (PMID 40678416, 2025). "The BAX and BCL2 genes are also involved in the regulation of apoptosis, which is a key process in the development and progression of cancer." (PMID 41203700, 2025). "Previous experiments revealed that IFN-γ-overexpressing BMSCs upregulated pro-apoptotic BAX expression, downregulated anti-apoptotic BCL2, and promoted apoptosis in cancer cells." (PMID 40642092, 2025). "BAX and BAK were amongst the most upregulated proteins following treatment of cancer cells with GTs." (PMID 41304887, 2025). "Antagonist administration also decreased the proliferation of cell lines and positively affected parameters such as NF‐kB, BAX, CAS‐3, and CAS‐9, which are thought to contribute to cancer pathogenesis." (PMID 40488271, 2025). "Owing to its involvement in apoptosis, BAX, along with other BCL-2 family proteins, has been investigated as a potential target for therapeutic interventions, particularly in cancer treatment." (PMID 41449208, 2025). "For cancer cells to survive their hostile environment, the anti-apoptotic BCL2 proteins must manage to keep the BH3-only proteins in check to prevent BAX/BAK pore formation and MOMP." (PMID 40113751, 2025). "In contrast, in cancer cells with elevated stress levels (e.g., cells in a deep, stable senescent state), BCL-xL binds to the effector proteins BAK and BAX." (PMID 41280927, 2025). "Regarding apoptosis in cancer cells, HKII acts as an anti-apoptotic molecule, competing directly with pro-apoptotic molecules such as BAX and BAK, and consequently prevents the release of cytochrome C (Cyt C) and inhibits apoptosis." (PMID 40801624, 2025). "MCL1 is known to disrupt BAK/BAX/caspase-3,7–dependent apoptosis, and pharmacological inhibition by AZD5991/S63845 inhibits the binding of BAK and BAX to MCL1, resulting in cancer cell death." (PMID 39846250, 2025). "BAK1 and BAX proteins play fundamental roles in apoptosis and seem to interact with VDAC proteins, whose expressions have been markedly altered in cancer, impacting their prognosis." (PMID 39449743, 2024).